AFP (alpha fetoprotein)
Diseases named in the same sentence as AFP in open-access papers (continued):
Sharing a sentence is not in itself a finding about the gene and the disease.
hepatoblastoma (continued). "The clinical evaluation of hepatoblastoma includes several well-established prognostic factors, such as the presence of metastatic disease at diagnosis, the pre-treatment extent of the tumor (PRETEXT stage), histological subtypes, and serum alpha-fetoprotein (AFP) levels." (PMID 39595571, 2024). "Notably, two of the patients in our study had a provisional diagnosis based on imaging and AFP levels and commenced neoadjuvant chemotherapy to manage their symptoms without a histological conformation of hepatoblastoma." (PMID 38201440, 2023). "For infant patients with normal AFP levels at diagnosis, and detailed cytogenetics on imaging results, an immunohistochemical and molecular analysis of INI-1protein might be useful in differential diagnosis between MRTL and hepatoblastoma." (PMID 38132242, 2023). "Standard of care off-therapy surveillance at our institution includes serial serum AFP monitoring along with risk-adapted radiographic imaging, the latter of which is controversial and not mandated on cooperative group trials of hepatoblastoma, noting that relapse with a normal AFP is uncommon." (PMID 37568737, 2023). "However, AFP is not sensitive or specific to hepatoblastoma and is also elevated in other liver malignancies." (PMID 36997898, 2023). "One sensitive but nonspecific biomarker for the presence of hepatoblastoma is AFP." (PMID 26465815, 2016). "AFP has also been demonstrated to be an excellent marker in predicting tumour recurrence during follow-up with one 10 year retrospective study reporting no imaging identifiable relapses from hepatoblastoma without an abnormal elevation of serum AFP levels." (PMID 27526937, 2016). "The delay in diagnosing hepatoblastoma was due to the fact that the newborn was 36 weeks old (not a VLBW), AFP was normal, and the initial liver tumor was interpreted as a metastasis of the pancreatic tumor." (PMID 35328311, 2022). "Serum AFP is elevated in tumors, including HCC, hepatoblastoma, and nonseminomatous germ cell tumors of the ovary and testis." (PMID 34746648, 2021). "We have investigated whether active transcription of the AFP gene may explain raised serum AFP concentrations in patients with HCC and hepatoblastoma by assaying human tumour and non-neoplastic tissue by molecular hybridization for the presence of mRNA encoding AFP." (PMID 2432915, 1986).
chronic hepatitis B (84 papers, 2008 to 2026). "Elevated AFP levels have been linked to liver damage, and in individuals with chronic hepatitis B, they rose in tandem with pathological levels of inflammation and fibrosis." (PMID 40284423, 2025). "The clustering in PG0 and PG1 showed significant association with sex, the degree of fibrosis, chronic hepatitis B status, prothrombin time and alpha fetoprotein levels (AFP)." (PMID 36737737, 2023). "The association between α-fetoprotein (AFP) levels with the assessment of liver stiffness (LS) in chronic hepatitis B (CHB) patients were explored." (PMID 33289529, 2021). "The SiNW-array FET for detecting HBV-DNA and AFP lays a solid foundation for the highly sensitive clinical detection of chronic hepatitis B." (PMID 41157439, 2025). "Numerous studies have shown that the concentration of AFP is a significant reference value for the clinical early diagnosis of chronic hepatitis B, liver cirrhosis, and liver cancer." (PMID 41157439, 2025). "A 60-year-old man with chronic hepatitis B presented with a liver mass, elevated alpha-fetoprotein levels, and imaging findings of heterogeneous arterial enhancement, all suggestive of HCC." (PMID 40429964, 2025). "Patient 3 was a 58-year-old male who presented with a history of chronic hepatitis B and elevated alpha-fetoprotein (AFP) levels, which prompted further evaluation." (PMID 38892779, 2024). "Chronic hepatitis B and Elevated levels of AFP were more common in HCC with HBDTT group than that of hilar CC group (p < 0.001)." (PMID 31969123, 2020). "The second trial, conducted in Toronto, Canada, on 1,069 participants with chronic hepatitis B, compared screening every six months with alpha-fetoprotein alone (n = 532) versus alpha-fetoprotein and ultrasound (n = 538) over a five-year period." (PMID 28813112, 2017). "In this study, only one patient who had chronic hepatitis B exhibited a slight increase in AFP, which could be attributed to inflammatory changes in the liver." (PMID 37492480, 2023). "Chronic hepatitis B (CHB) is one of the most common non-malignant causes of false positive AFP in GCTs." (PMID 31836006, 2019). "However, serum AFP levels decreased following anti-viral therapy in patients with chronic hepatitis B, and in those patients who demonstrated elevated AFP levels after anti-viral therapy, the risk of HCC was high." (PMID 27304617, 2016). "However, reported sensitivity and specificity of AFP varied widely in chronic hepatitis B (CHB) patients: 33–72% and 35–100%, respectively, at the cut-off of 20 ng/mL in recent literatures." (PMID 27997559, 2016). "Our patient was diagnosed with acute exacerbation of chronic hepatitis B, and we presumed that this condition might be related to extremely elevated alpha-fetoprotein." (PMID 27246404, 2016). "Aurora B overexpression was associated with high serum AFP level (≥200 ng/mL; P < 0.0001), but not with age, gender, chronic hepatitis B/C virus infection, or liver functional reserve (Child-Pugh class)." (PMID 20799978, 2010). "In patients with chronic hepatitis B, not only is the concentration of HBV virus high, but there is also an increase in the concentration of the disease marker Alpha-fetoprotein (AFP)." (PMID 41157439, 2025). "In conclusion, we were able to demonstrate that the biomarker-based GALAD score clearly outperforms the biomarkers AFP, DCP and AFP-L3 used individually for early-stage HCC detection in a Caucasian cohort of chronic hepatitis B or C patients." (PMID 34451832, 2021). "We report here a patient with chronic hepatitis B and normal liver related blood values presenting with a surgically removed primary TGCT and elevated AFP levels." (PMID 31906360, 2020). "In cohort B, which comprised 447 subjects, including patients with HCC, LC, and chronic hepatitis B as well as HC, the accuracy of DCP was further elevated (12.3–20.67% higher than that of AFP)." (PMID 27070780, 2016).
chronic hepatitis B (continued). "Histopathological examination showed chronic hepatitis B in the background liver and the immunohistochemical (IHC) findings strongly supported the diagnosis of ICC with aberrant expression of AFP." (PMID 27301956, 2016). "This study aimed to investigate the relationship between serum alpha-fetoprotein (AFP) levels and pathological stages of liver biopsy in patients with chronic hepatitis B (CHB)." (PMID 25128299, 2014). "Among the patients with chronic hepatitis B (CHB), the AFP value exceeded 20 ng/mL for 2 patients and was <20 ng/mL for 7 patients." (PMID 24927126, 2014). "When AFP was negative, sST2 showed better diagnostic performances in distinguishing HCC from the healthy (AUC = 0.868), but poorer from chronic hepatitis B (AUC = 0.707)." (PMID 39677962, 2024). "This study assessed the cost–effectiveness of seven different screening strategies for patients with chronic hepatitis B (CHB) in China: ultrasonography (US), alpha-fetoprotein (AFP), protein induced by vitamin K absence-II (PIVKA-II), AFP+US, AFP+PIVKA-II, GAAD and GAAD+US." (PMID 38415341, 2024). "Thus, ALT, AFP (alpha-fetoprotein) and platelet count were recently evaluated in a prognosis score for HCC in CHB (chronic hepatitis B) patients." (PMID 37998561, 2023). "The following pre-operative factors were calculated in univariate analysis: recipient age, recipient sex, chronic hepatitis B virus infection, chronic hepatitis C virus infection, MELD score, pre-LT serum NLR, pre-LT locoregional treatment, serum AFP level, donor age, and donor sex." (PMID 35735419, 2022). "Eighty percent of our patient in our country is presented with chronic hepatitis B. For patients presented with a tumor on the caudate lobe, we have no AFP level limit, due to the difficulty in the technique of TACE for tumor on this region." (PMID 35115011, 2022). "However, a recent study showed that adding DCP did not further improve the sensitivity of AFP and AFP-L3 combination in patients with cirrhosis and/or chronic hepatitis B." (PMID 37568696, 2023). "However, we present a case of significantly elevated serum alpha-fetoprotein without evidence of malignant disease in a patient who is a carrier of chronic hepatitis B." (PMID 27246404, 2016). "We report a rare case of extremely elevated alpha-fetoprotein due to acute exacerbation of chronic hepatitis B without any malignancy, and a decrease in this tumor marker simultaneous with a decrease in hepatitis B virus deoxyribonucleic acid copy number on entecavir treatment." (PMID 27246404, 2016). "Although this patient possessed a 20-year history of chronic hepatitis B, which could be a possible reason for elevated serum AFP, the existence of cancer stem cells should not be excluded." (PMID 25624892, 2015). "The results showed that serum ANGPTL6 could effectively differentiate between HBV-related early HCC patients with normal serum alpha-fetoprotein (AFP) levels and the noncancer group (healthy participants and chronic hepatitis B patients) (AUC = 0.717, 95% CI: from 0.614 to 0.805)." (PMID 36421714, 2022). "There have been case reports with regard to abnormally elevated AFP levels in patients with chronic hepatitis B or C infections without evidence of HCC, and elevated serum AFP levels decreased in response to antiviral therapy." (PMID 33490235, 2020). "However, increased circulating alpha fetoprotein (AFP), the most commonly used circulating biomarker for HCC, has been observed in patients without HCC, such as those with chronic hepatitis B or C, suggesting the poor specificity of AFP for HCC." (PMID 32309434, 2020).
seminoma (80 papers, 1995 to 2025). A radiosensitive malignant germ cell tumor found in the testis (especially undescended), and extragonadal sites (anterior mediastinum and pineal gland). "When we adjusted stratified for factors such as age, clinical stage, alpha-fetoprotein, beta-hCG, lactate dehydrogenase, and histology non-seminoma, there was persistent the risk of recurrence (Figure-2A)." (PMID 32167697, 2020). "Factors associated with high VD included non-seminoma type (p = 0.016), AFP ≥ 14.7 ng/mL (p = 0.0001), and hCG ≥ 25 mIU/mL (p = 0.0001)." (PMID 19709439, 2009). "Specifically, the SUVmax could differentiate seminomas and NSGCTs among malignant MGCTs and may be associated with AFP levels." (PMID 37848723, 2023). "Alpha–fetoprotein elevation has been associated with chronic liver diseases and a limited number of cancers (hepatic primary tumors and metastases, bile duct, pancreatic, gastric and lung cancer, and non–seminoma germ–cell tumors)." (PMID 28407756, 2017). "The frequency of elevated AFP in the seminoma group was at least 4.1%, compared with 1.6% in the reference population." (PMID 39934683, 2025). "The American Society of Clinical Oncology (ASCO) identifies three key serum markers for seminoma: elevated AFP, increased β-hCG, and LDH exceeding 1.5 times normal levels." (PMID 40492123, 2025). "Elevated serum human chorionic gonadotropin (β-hCG) and alpha-fetoprotein (AFP) concentrations are present in about 60% of all males with NSGCTs, while β-hCG is only increased in serum in about 20% of men with seminomas." (PMID 39565383, 2025). "For the seminoma patients included in this study, the CVi for AFP was 10.3%, higher than the 4.5% quoted in reference databases." (PMID 39934683, 2025). "Inflammatory indices (NLR and MPV/PLT) were higher in non-seminoma cases and showed positive correlations with AFP and β-HCG, suggesting a link between systemic inflammation and tumor activity." (PMID 41527642, 2025). "NSGCTs, especially those containing a component of YST, can exhibit increased alpha-fetoprotein levels and proportionally higher levels in advanced disease stages, whereas this is mostly expected in patients with pure seminoma." (PMID 41209905, 2025). "For seminoma patients, the sensitivities of AFP, β-hCG, and LDH were 2.3%, 31%, and 28%, respectively, and 46% for all 3 STMs combined." (PMID 39685906, 2024). "Among all men with testicular GCT (NSGCT and seminoma), Dieckmann and investigators found in their study that the sensitivity of AFP was 18%, β-hCG 35%, LDH 28%, and about 50% for all three STMs combined." (PMID 39685906, 2024). "In this case, although OCT-3/4 positivity was noted, the lack of staining for CD117 and CD30 on immunohistochemistry and the raised serum AFP levels excluded the close differentials of seminoma and embryonal carcinoma." (PMID 39363907, 2024). "For seminoma patients, the sensitivities of AFP, β-hCG and LDH was 2.3%, 31%, and 28%, respectively, and 46% for all 3 STMs combined." (PMID 39685906, 2024). "Testicular tumors histologically described as seminomas occurring simultaneously with the presence of an elevated serum AFP is a rare clinical finding as described in this case." (PMID 37485120, 2023). "While non-seminoma PMGCTs are associated with high levels of LDH, AFP, and βHCG, around 20% of seminomas are characterized by elevated βHCG and LDH." (PMID 36831022, 2023). "Most probably, these elevations represent idiopathic unspecific elevations similar to the AFP elevations in seminoma." (PMID 36869885, 2023). "AFP is elevated in embryonal carcinoma, yolk sac tumors, and teratoma; βHCG is elevated in seminoma, choriocarcinoma, and embryonal carcinoma." (PMID 36831022, 2023). "In this case, this patient was treated with adjuvant chemotherapy including bleomycin, etoposide, and cisplatin for a histologically described seminoma with initial and persistently elevated serum AFP." (PMID 37485120, 2023).
seminoma (continued). "One case series describes the finding of serum AFP elevations in approximately 2% of patients with histologically pure seminomas arising from the testicle." (PMID 37485120, 2023). "In a recent case series with five seminoma patients and elevated AFP-values also below 20 ng/ml, AFP remained unchanged after chemotherapy treatment." (PMID 34854948, 2022). "In all subpopulations, the expression rates of all tumour markers increased with increasing tumour sizes, except for AFP in the seminoma subgroup (Cochran–Armitage trend test, all except seminoma p < 0.0001; seminoma p = 0.9133)." (PMID 36358866, 2022). "Specifically, our study brings the novelty of including a seminoma with constitutional elevation of AFP." (PMID 35756620, 2022). "We considered serum AFP levels in our survival modeling because AFP is a surrogate biomarker for non-seminoma testicular cancers." (PMID 35804904, 2022). "Very few seminoma patients (2.8%) had elevations of AFP that were obviously unrelated to the malignant disease." (PMID 31275973, 2019). "High biomarker levels are noted in 50–70% of patients with non-seminomas, thus AFP is the most commonly elevated tumour marker in TC." (PMID 31652641, 2019). "First, the elevated β-HCG, the normal AFP, and overall clinical picture suggested that this was a seminoma, and second, the location of the lesion would result in a surgical risk and morbidity that would outweigh any potential benefit." (PMID 30563561, 2018). "In our case, since the lesion was thought to be a seminoma (normal AFP), monitoring with FDG-PET would be in keeping with consensus guidelines." (PMID 30563561, 2018). "Viable cancer cells were observed in the retroperitoneal lymph nodes of 15 patients (37.5 %) with pure seminoma showing elevated serum AFP levels." (PMID 27150447, 2016). "Although his testicular histology showed pure seminoma at orchiectomy, preoperative serum AFP levels were elevated." (PMID 27150447, 2016). "In the non-seminoma group, 2 (28.57%) had raised AFP, 1 (14.29%) raised B-HCG, 2 (28.57%) raised both markers and 2 (28.57%) cases normal." (PMID 29147233, 2011). "Chemotherapy represented the initial step of salvage treatment in four of five non-seminoma patients with elevated HCG/AFP." (PMID 16508636, 2006). "Therefore, while it is striking that the prevalence of AFP elevations in the cohort described is similar to the ~ 5% prevalence of FOXA2-positive seminomas reported in prior studies, it is difficult to ascribe the patterns observed to this mechanism." (PMID 39934683, 2025). "However, the authors suggest that the role of transcription factors and epigenetics in reprogramming micro populations of AFP-producing seminomas warrants further investigation." (PMID 39934683, 2025). "Thus, elevated AFP was at least 2.6 times more frequent amongst seminoma patients in this study than in the reference population." (PMID 39934683, 2025). "Even though biomarkers are included in international surveillance guidelines, high-quality evidence on their accuracy, optimal thresholds, and the most effective surveillance strategies using modern investigative techniques remains limited, especially for AFP levels in pure seminomas." (PMID 40723290, 2025). "In Group 4, R‐RPLND was performed in 30 patients with CS II‐III non‐seminoma, two patients with pure seminoma with uncertain non‐seminoma content (due to elevated alpha‐fetoprotein), one patient with a seminomatous late relapse, and one patient with a pure seminoma with ureteric obstruction." (PMID 40260829, 2025). "In contrast, serum AFP levels typically remain normal in seminoma cases." (PMID 39045558, 2024). "Noteworthy, AFP was found to be elevated in 5.2% of seminoma patients." (PMID 36869885, 2023).